EHMT1 (euchromatic histone lysine methyltransferase 1)
Description:
Histone methyltransferase that specifically mono-, di- and trimethylates 'Lys-9' of histone H3 (H3K9me1, H3K9me2 and H3K9me3, respectively) in euchromatin. H3K9me represents a specific tag for epigenetic transcriptional repression by recruiting HP1 proteins to methylated histones. Also weakly methylates 'Lys-27' of histone H3 (H3K27me). Also required for DNA methylation, the histone methyltransferase activity is not required for DNA methylation, suggesting that these 2 activities function independently (By similarity). Probably targeted to histone H3 by different DNA-binding proteins like E2F6, MGA, MAX and/or DP1. During G0 phase, it probably contributes to silencing of MYC- and E2F-responsive genes, suggesting a role in G0/G1 transition in cell cycle. Involved in the differentiation of myoblastic precursors into brown adipose cells: following recruitment to chromatin by PRDM16, mediates formation of H3K9me2 and H3K9me3, inhibiting the expression of white adipose-selective genes (By similarity). Also involved in the differentiation of beige adipocytes from white adipose cells following recruitment by PRDM16 (By similarity). EHMT1 also promotes protein stabilization of PRDM16, by preventing PRDM16 ubiquitination and degradation (By similarity). Represses the expression of mitochondrial function-related genes, perhaps by occupying their promoter regions, working in concert with probable chromatin reader BAZ2B (By similarity).
Synonyms: Eu-HMTase1; GLP; GLP1; EUHMTASE1; KIAA1876; KMT1D; FLJ12879; bA188C12.1; FLJ40292; EHMT1-IT1; FP13812; KLEFS1
Tractability: Small molecule: a structure with a bound ligand is known; a high-quality ligand is known; it has a high-quality binding pocket; it belongs to a druggable protein family. PROTAC: UniProt records ubiquitination sites on it; ubiquitination databases record sites on it; its protein half-life has been measured; a small molecule that binds it is known.
Target class: Writer; Protein methyltransferase; Epigenetic regulator
Chemical probes: A-366 (high quality), UNC0638 (high quality), UNC0642 (high quality)
Gene: Protein-coding gene on chromosome 9 (137,618,977 to 137,870,016, forward strand). Ensembl gene ENSG00000181090.
Subcellular location: Nucleus; Chromosome
Subcellular location (Human Protein Atlas): Nuclear bodies; Nucleoplasm
Pathways (Reactome):
Gene expression (Transcription): Regulation of endogenous retroelements by the Human Silencing Hub (HUSH) complex; Transcriptional Regulation by E2F6; Transcriptional Regulation by VENTX
Cellular responses to stimuli: Senescence-Associated Secretory Phenotype (SASP)
Chromatin organization: PKMTs methylate histone lysines
Gene Ontology:
Molecular function: histone H3K9 methyltransferase activity; histone H3K9 monomethyltransferase activity; methyltransferase activity; protein binding; protein-lysine N-methyltransferase activity; transcription corepressor binding; histone H3K27 methyltransferase activity; histone H3K9 trimethyltransferase activity; histone H3K9me2 methyltransferase activity; histone H3 methyltransferase activity; histone methyltransferase activity; zinc ion binding
Biological process: chromatin organization; peptidyl-lysine dimethylation; beige fat cell differentiation; brown fat cell differentiation; DNA methylation-dependent constitutive heterochromatin formation; epigenetic regulation of gene expression; negative regulation of DNA-templated transcription; negative regulation of transcription by RNA polymerase II; negative regulation of white fat cell differentiation; peptidyl-lysine monomethylation; positive regulation of cold-induced thermogenesis; regulation of embryonic development; response to fungicide
Cellular component: nuclear body; nucleoplasm; nucleus; chromatin; chromosome
Genetic constraint (gnomAD): Loss-of-function variants: 15 observed, 144.98 expected, observed/expected ratio (o/e) 0.1, 90% interval 0.068 to 0.16. The upper end of that interval is the gene's LOEUF score, 0.16, which puts it in group 1 of 6, group 1 being the genes least tolerant of losing a copy. Missense variants: 1,577 observed, 1,808.8 expected, observed/expected ratio (o/e) 0.87, 90% interval 0.84 to 0.91. Synonymous variants: 785 observed, 725.62 expected, observed/expected ratio (o/e) 1.08, 90% interval 1.02 to 1.15.
Gene-disease validity (ClinGen):
ClinGen rates the evidence that EHMT1 causes each of these diseases.
Kleefstra syndrome (autosomal dominant): Definitive. A genetic disorder characterized by intellectual disability, childhood hypotonia, severe expressive speech delay and a distinctive facial appearance with a spectrum of additional clinical features.
Homologues: Orthologues: macaque EHMT1 (99% identical), rabbit EHMT1 (90% identical), rat Ehmt1 (89% identical), mouse Ehmt1 (89% identical), dog EHMT1 (88% identical), guinea pig Ehmt1 (86% identical), pig EHMT1 (82% identical), chimpanzee EHMT1 (71% identical), tropical clawed frog ehmt1 (63% identical), zebrafish ehmt1b (54% identical), zebrafish ehmt1a (40% identical), Drosophila melanogaster G9a (28% identical), and 13 more. Paralogues in human: EHMT2 (44% identical), KMT2A (16% identical), SETDB1 (15% identical), KMT2C (14% identical), KMT2B (14% identical), KMT2D (14% identical), NSD1 (13% identical), ASH1L (13% identical), NSD2 (12% identical), NSD3 (12% identical), SETD1B (12% identical), SETD1A (11% identical), and 7 more.
Diseases named in the same sentence as EHMT1 in open-access papers:
EHMT1 is named in the same sentence as 94 diseases in open-access papers, as found by Europe PMC text mining. Sharing a sentence is not in itself a finding about the gene and the disease. The quoted sentences say what the papers report.
Kleefstra syndrome (66 papers, 2011 to 2026). "Kleefstra syndrome (KS), a rare neurodevelopmental disorder caused by alterations in the EHMT1 gene, has been associated with various cardiac abnormalities, including structural defects and arrhythmias." (PMID 41654978, 2026). "Beyond Kleefstra syndrome, mutations in EHMT1 have been implicated in other neurodevelopmental disorders, including ASD and global developmental delay (GDD)." (PMID 40469903, 2025). "Kleefstra syndrome is a disorder characterized by severe mental retardation, seizures, and behavioral abnormalities and is often linked to EHMT1 gene mutations." (PMID 39976094, 2025). "A study involving excitatory cortical neurons derived from induced pluripotent stem cells obtained from Kleefstra syndrome patients exhibited EHMT1 deficiency-triggered NMDAR hyperactivity." (PMID 40400398, 2025). "A handful of genes participate in the opposing process of repressing DNA via methylation of lysine residues of histone 3 at position 9 (e.g., the H3K9 methyltransferase EHMT1, mutated in those with Kleefstra Syndrome)." (PMID 40612695, 2025). "Kleefstra syndrome (caused by EHMT1 haploinsufficiency) is one of the project’s exemplar “chromatinopathies”, alongside certain synaptic disorders (“SNAREopathies”)." (PMID 40968989, 2025). "In Kleefstra syndrome, mutations or deletions of the EHMT1 gene impair its ability to regulate chromatin structure, leading to abnormal gene expression that disrupts neuronal development and function." (PMID 40469903, 2025). "Kleefstra syndrome (KS) is a rare neurodevelopmental disorder associated with disruptions in the EHMT1 gene, often leading to intellectual disability, autism spectrum behaviors and epilepsy." (PMID 40968989, 2025). "This ambitious design will enable direct comparisons between a child’s EEG features and their neuronal cell biology, providing unprecedented insight into how a genetic mutation (like EHMT1 in Kleefstra syndrome) leads to network-level dysfunction." (PMID 40968989, 2025). "One of the most well-known disorders associated with EHMT1 mutations is Kleefstra syndrome (KS; OMIM 610253), a rare genetic condition characterized by intellectual disability (ID), childhood hypotonia, and distinctive facial features." (PMID 40469903, 2025). "Kleefstra syndrome emerges from the haploinsufficiency of EHMT1 due to either a deletion at 9q34.3 or pathogenic variants of EHMT1." (PMID 40400398, 2025). "Kleefstra syndrome (KS) is a rare neurodevelopmental disorder caused by either a 9q34.3 terminal microdeletion or loss-of-function variants in the EHMT1 gene." (PMID 40968989, 2025). "First, we examined TXGNN’s predictions for Kleefstra syndrome, a rare disease caused by mutations in the EHMT1 gene." (PMID 39148855, 2024). "The 9q34 breakpoint interrupts intron 25 of the gene EHMT1, haploinsufficiency of which causes Kleefstra syndrome 1 (MIM#610253), a diagnosis fitting the clinical phenotype (Supplemental Document 1)." (PMID 39486878, 2024). "One breakpoint disrupted EHMT1 likely leading to loss of function of the gene, consistent with the expected underlying biological mechanism for Kleefstra syndrome 1 (MIM#610253), as supported by the RNA results." (PMID 39486878, 2024). "The functions of EHMT1 and EHMT2 have been implicated in neurodevelopmental disorders, including Kleefstra syndrome and Prader-Willi syndrome, and EHMT1 has been identified as a schizophrenia susceptibility gene." (PMID 38472451, 2024). "Cell cycle progression contributes to pathobiological mechanisms underlying Kleefstra syndrome, which is a congenital disease caused by EHMT1 mutations." (PMID 37782747, 2023).
Kleefstra syndrome (continued). "the whole genome sequencing project he participated in around the age of 30 and received a diagnosis of Kleefstra syndrome with a variant in the EHMT1 gene." (PMID 37575568, 2023). "In this proof-of-principle study we assess a Kleefstra Syndrome patient’s known pathogenic EHMT1 genetic variant." (PMID 35139903, 2022). "In this study a patient with a genetic variant in the EHMT1 gene is assessed with relevance to Kleefstra Syndrome." (PMID 35139903, 2022). "Kleefstra syndrome is caused by EHMT1 haploinsufficiency that results in partial or complete loss of EHMT1 expression." (PMID 35139903, 2022). "EHMT1 is an epigenetic repressor that is causal for Kleefstra Syndrome (KS), a genetic disorder linked with neurodevelopmental disorders and associated with schizophrenia." (PMID 36216811, 2022). "EHMT1 haploinsufficiency, a hallmark of Kleefstra syndrome, was confirmed in the EHMT1_SNV cells by decreased EHMT1 protein expression." (PMID 35139903, 2022). "Six other genes potentially involved in ID were included, namely ASCC3 found mutated in a single family by performing a large-scale genomic study, EHMT2 homologous to EHMT1 causing Kleefstra syndrome, and CDK8." (PMID 36551904, 2022). "Another promising candidate, Kleefstra syndrome–associated euchromatic histone lysine methyltransferase 1 EHMT1 at 9q34.3, encoding a SOX11-interacting methyltransferase." (PMID 33658318, 2021). "Kleefstra syndrome is caused by haploinsufficiency of the euchromatin histone methyltransferase 1 (EHMT1) and characterized by ASD and other comorbid symptomatology as intellectual disability and a delayed psychomotor development." (PMID 33431980, 2021). "It is possible that G9a-mediated stress tolerance also plays a role in coping with these normal metabolic adaptations, potentially explaining developmental and cognitive problems in Kleefstra syndrome, caused by loss of the G9a ortholog EHMT1." (PMID 34030685, 2021). "Its loss in tumors prevents cancer progression, however, germline mutations in its close paralog and binding partner EHMT1 cause the severe neurodevelopmental disorder Kleefstra syndrome." (PMID 34030685, 2021). "Haploinsufficiency of EHMT1 is known to cause Kleefstra syndrome 1 in an autosomal dominant manner (OMIM #610253)." (PMID 34616436, 2021). "Of note, mutations in the G9a orthologue EHMT1 in humans cause Kleefstra syndrome, a neurodevelopmental disorder that is characterized by intellectual disability and autism and that also shows neurodegenerative features." (PMID 30860988, 2019). "Kleefstra syndrome is caused by deletions or mutations of the EHMT1 gene, encoding a histone methyltransferase, and, like PMS, presents with ID, ASD, severe speech deficits, and hypotonia, in addition to distinctive facial features." (PMID 31879555, 2019). "A germline genetic defect affecting the euchromatin histone methyltransferase 1 (EHMT1) gene causes Kleefstra syndrome, which is associated with the typical triad of distinct facial appearance, (childhood) hypotonia, and intellectual disability." (PMID 29416845, 2018). "Exome sequencing identified a novel, de novo splice site variant NM_024757.4: c.2750‐1G>T in EHMT1, a candidate gene for Kleefstra syndrome, in the patient that results in exon skipping and downstream frameshift and termination." (PMID 28361099, 2017). "Kleefstra syndrome, caused by haploinsufficiency of euchromatin histone methyltransferase 1 (EHMT1), is characterized by intellectual disability (ID), autism spectrum disorder (ASD), characteristic facial dysmorphisms, and other variable clinical features." (PMID 29069077, 2017). "Kleefstra syndrome (KS) is a rare autosomal dominant developmental disability, caused by microdeletions or intragenic mutations within the epigenetic regulator gene EHMT1 (euchromatic histone lysine N‐methyltransferase 1)." (PMID 28361099, 2017).
Kleefstra syndrome (continued). "Kleefstra syndrome (OMIM #610253) is a neurodevelopmental disorder that is caused by haploinsufficiency of EHMT1." (PMID 29069077, 2017). "In mouse knockout models, loss of Ehmt1 causes phenotypes that are reminiscent of Kleefstra Syndrome, including deficits in learning and memory, increased anxiety, hypotonia, cranial abnormalities, and developmental delay." (PMID 29069077, 2017). "Although Kleefstra syndrome has been associated with dendritic and synaptic defects in mice and Drosophila, little is known about the role of EHMT1 in the development of cortical neuronal networks." (PMID 27767173, 2016). "Heterozygous mutations or deletions in the human Euchromatin histone methyltransferase 1 (EHMT1) gene cause Kleefstra syndrome, a neurodevelopmental disorder that is characterized by autistic-like features and severe intellectual disability (ID)." (PMID 27767173, 2016). "A deletion containing the GLP/EHMT1 gene (euchromatin histone methyltransferase 1) causes Kleefstra syndrome, a developmental severe IDD, with defects in learning, motivation, and environmental adaptation." (PMID 27547454, 2016). "Heterozygous mutations or deletions of the human EHMT1 gene cause Kleefstra Syndrome (OMIM #610253), a neurodevelopmental disorder that is characterized by autistic-like features and severe intellectual disability." (PMID 21245904, 2011). "Excellent candidates are histone modifiers that are involved in intellectual disability, such as EHMT1, implicated in Kleefstra Syndrome." (PMID 21245904, 2011). "Our findings are relevant to the pathophysiological mechanisms underlying Kleefstra Syndrome, a severe form of intellectual disability caused by mutations in human EHMT1, and have potential therapeutic implications." (PMID 21245904, 2011). "Furthermore, neuron-specific deficiency of EHMT1/2 leads to defects in learning, motivation and environmental adaptation in mice, similar to the key symptoms of Kleefstra syndrome." (PMID 38472451, 2024). "Out of the constraint overlapped genes (1086 genes), we shortlisted three genes, one with possible studied pleiotropism of NDDs and CAs: EHMT1, which causes Kleefstra syndrome, known to harbor heterozygous intragenic EHMT1 pathogenic variants from heterozygous deletions at chromosome 9q34.3." (PMID 36383254, 2023). "As proof-of-principle, we investigated an EHMT1 (Euchromatin histone methyltransferase 1; EHMT1 c.3430C > T; p.Gln1144*) genetic variant pathogenic for Kleefstra syndrome and determined changes in gene expression during neuronal progenitor cell differentiation." (PMID 35139903, 2022). "Since LoF variants in EHMT1 give rise to Kleefstra syndrome, it is tempting to speculate that EHMT2 is a candidate for syndromic ID as well." (PMID 36551904, 2022). "Defects in EHMT1 are a cause of Kleefstra Syndrome, a genetic disorder linked with schizophrenia." (PMID 36618913, 2022). "In contrast, haploinsufficiency of the histone methyltransferase Ehmt1 (Kleefstra Syndrome) causes delayed maturation of PV + neurons in the mouse sensory cortices, consisting of delayed PV expression and PNN generation, as well as reduced GABAergic neurotransmission." (PMID 33263776, 2021). "Indeed, mutations in EHMT1/GLP cause Kleefstra syndrome, which is a great example of an emerging group of intellectual disability disorders caused by genes encoding epigenetic regulators of neuronal gene activity." (PMID 30305677, 2018). "Interestingly, clinical annotation using Carpe Novo software package revealed EHMT1 is a candidate gene associated with Kleefstra syndrome – a disease characterized by symptoms which were all found present in our proband." (PMID 28361099, 2017).